TSLP (thymic stromal lymphopoietin)
Diseases named in the same sentence as TSLP in open-access papers (continued):
Sharing a sentence is not in itself a finding about the gene and the disease.
asthma (continued). "A multitude of humanized monoclonal antibodies for asthma treatment are currently undergoing clinical development, which include tezepelumab (targeting TSLP) as well as etokimab, itepekimab, astegolimab (AMG 282), torzorakimab, and melrilimab (GSK3772847) for IL-33." (PMID 36311787, 2022). "Thymic stromal lymphopoietin (TSLP) is a Th2-like cytokine involved in asthma pathogenesis." (PMID 35292112, 2022). "A possible mechanism behind this phenomenon could be thymic stromal lymphopoietin (TSLP) which is a regulator in asthma inflammation and increased by triggers such as pollutants." (PMID 35686373, 2022). "Anti-TSLP therapy has now been approved for treatment of asthma, with tezepelumab demonstrating significant attenuation of allergen-induced asthmatic responses and improvement in asthma exacerbation rate through a reduction in blood eosinophils and airway nitric oxide levels." (PMID 35406669, 2022). "ILC2s do not depend on T cells and secrete a large number of type 2 cytokines (such as IL-4, IL5, IL-9, and IL-13) under the function of IL-25, IL-33 and thymic stromal lymphopoietin (TSLP) to participate in asthma, virus infection and worm-host defense related with the type 2 immune response." (PMID 33514798, 2021). "Retinoic acid also promotes the production of IgA in the presence of loTSLP and may thus be able to restore IgA production in asthma patients in the presence of aberrant TSLP signaling." (PMID 33808333, 2021). "Furthermore, the potential efficacy of tezepelumab should also be explored with regard to its possible therapeutic application in T2-low neutrophilic asthma, given the relevant contribution of TSLP to the pathophysiology of this difficult-to-treat endotype." (PMID 33922072, 2021). "This indicates that the more prominent accumulation of airway ATP may be responsible for the elevated IL-25 and TSLP expression in type 2–high asthma." (PMID 33945508, 2021). "Administration of anti-IL-25 and anti-TSLP antibodies during ovalbumin-induced asthma could reduce the infiltration of inflammatory cells into airways, as well as local expression of IL-4, IL-5 and IL-13." (PMID 34084159, 2021). "Lastly, because of the biologic activities exerted by TSLP on airway structural cells, current trials will probably also provide interesting information about the supposed ability of tezepelumab to modulate bronchial remodeling in severe asthma." (PMID 33922072, 2021). "Nevertheless, taking into account the impressive results with anti-TSLP therapy in severe asthma, one may expect that in such case combined anti-IL-33 and anti-TSLP therapy could be even more beneficial." (PMID 34084159, 2021). "We conclude that the overproduction of oxidative stress markers and TSLP may be an important aspect in AD-related asthma." (PMID 34522948, 2021). "Moreover, in a phase 2 trial addition of Tezepelumab, a TSLP blocking agent, resulted in attenuated asthma exacerbation rates in severely affected patients with uncontrolled asthma." (PMID 34084159, 2021). "TREM2 up showed enrichment in ‘Immune response_TSLP signaling’ (P = 3.0E‐7), ‘Th2 cytokine‐induced alternative activation of alveolar macrophages in asthma’ (P = 1.1E‐06), and ‘Immune response_IL‐4‐induced regulators of cell growth, survival, differentiation, and metabolism’ (P = 1.2E‐06)." (PMID 34523252, 2021). "Moreover, tezepelumab should also be investigated for its potential therapeutic effects in T2-low neutrophilic asthma, possibly due to the interferences with the pathophysiologic actions exerted by TSLP- in IL-17-mediated airway inflammation." (PMID 34572294, 2021). "Indeed, tezepelumab, a fully human anti-TSLP monoclonal antibody, has been shown to improve asthma control and FEV1 and reduce exacerbations, blood eosinophyl count, FENO and total serum IgE in phase II trials." (PMID 34680614, 2021). "Together, these studies suggest that the CD39–extracellular ATP axis may regulate IL-25, IL-33, and TSLP in asthma." (PMID 33945508, 2021).
asthma (continued). "Consequently, more extracellular ATP was accumulated, leading to higher expression of IL-25 and TSLP and more prominent type 2 inflammation in type 2–high asthma." (PMID 33945508, 2021). "Released from airway epithelial cells upon tissue damage induced by several noxious agents including allergens, viruses, bacteria, and airborne pollutants, TSLP activates dendritic cells and group 2 innate lymphoid cells involved in the pathobiology of T2-high asthma." (PMID 33922072, 2021). "Moreover, airway expression levels of TSLP are correlated with asthma severity and airflow limitation." (PMID 33922072, 2021). "Oxidative stress has been identified as an elicitor of TSLP production, although this has not been proven in the skin, and IL-33 and IL-25, have been linked to it in other allergic diseases such as asthma." (PMID 34944487, 2021). "Together with IL-33, thymic stromal lymphopoietin (TSLP) is widely recognized as a critical factor in allergic disorders, including rhinitis, asthma, food allergy, eosinophilic esophagitis, and atopic dermatitis (AD), i.e., conditions, in which MCs act as critical effector cells." (PMID 33429916, 2021). "Furthermore, it can significantly reduce IgE, histamine, and TSLP production in a mouse model of asthma." (PMID 34931126, 2021). "Indeed, TSLP plays a strategic role in asthma pathobiology, due to its top position located at a very upstream level within the complex network of cellular and molecular pathways leading to airway inflammation." (PMID 33922072, 2021). "Given the relevant importance of TSLP as a master player of asthma pathobiology, this alarmin, acting as an upstream inducer of strategic proinflammatory and remodeling pathways, appears to be a potential suitable target for perspective biological therapies of severe asthma." (PMID 33922072, 2021). "TSLP is produced in a short (shTSLP) form of 63 amino acids under homeostatic conditions and in a long form (loTSLP) of 159 amino acids following viral infection and in asthma." (PMID 33808333, 2021). "Additional insight into the role of TSLP in regulating IgA production could be obtained using B cells from asthma patients." (PMID 33808333, 2021). "Due to its activity early in the inflammation cascade, blockade of TSLP may be suitable for a broad population of patients with severe, uncontrolled asthma." (PMID 33917396, 2021). "This combination of biomarkers (high TSLP levels and low tryptase levels) might indicate that these patients with severe asthma are suitable for anti-TSLP therapy." (PMID 33875671, 2021). "We hypothesized that the differentially expressed epithelial miRNAs between the 2 asthma subsets may contribute to IL-25, IL-33, and TSLP expression in asthma." (PMID 33945508, 2021). "As a consequence, the anti-TSLP antibody tezepelumab is in clinical trials for asthma and AD." (PMID 33429916, 2021). "Collectively, serum TSLP may contribute to steroid resistance, whereas tryptase may suggest steroid responsiveness in asthma inflammatory process, as observed in the present study." (PMID 33875671, 2021). "Targeting TSLP – upstream mediator triggered at the beginning of the inflammatory response – has emerged as a promising alternative treatment in patients with severe asthma." (PMID 34608100, 2021). "TSLP-specific antibodies are used to ameliorate disease in asthma patients." (PMID 34659250, 2021). "In conclusion, in the Th2 cytokine milieu of asthma, FLG deficient mutation in airway epithelial cells may increase the epithelial permeability and the expression of IL-33/TSLP which positively feedback the Th2 inflammation response." (PMID 34484176, 2021). "Multiple triggers contribute to mast cell activation in asthma including stimulation of the high affinity IgE receptor FcεRI by allergens, ligands of the Toll like receptors, and cytokines activating the alarmin receptors (TSLP, IL-33)." (PMID 35387008, 2021).
asthma (continued). "Targeting TSLP and alarmins, at the top of the inflammatory cascade, might be the new frontier to conquer in the battle against asthma." (PMID 34608100, 2021). "Ultimately, therapies targeting development of Th2 cells, such as those blocking the IL-4Rα or the cytokine TSLP, may prove the most effective in reducing persistence of asthma symptoms." (PMID 33076829, 2020). "Thymic stromal lymphopoietin (TSLP) is an epithelial-derived cytokine (also termed an ‘alarmin’) implicated in the initiation and persistence of airway inflammation, and is a key upstream regulator of many inflammatory pathways in asthma." (PMID 33050928, 2020). "Based on the outcome of in vitro and in vivo studies, it is thought that RV may enhance Th2 cytokines via the expression of TSLP and IL-25 derived from airway epithelial cells; thus, exacerbating the lung disease in patients with asthma." (PMID 32637363, 2020). "In light of the strong indication that they act as upstream drivers of T2-mediated disease, TSLP, IL-33, and IL-25 have attracted a lot of interest as potential therapeutic targets in asthma, and monoclonal antibodies targeting TSLP and IL-33 are currently under clinical evaluation." (PMID 33255348, 2020). "Furthermore, clinical trials have now provided strong evidence for a central role of TSLP as an important modulator in asthma." (PMID 33255348, 2020). "The results of our study show that periostin and TSLP are associated with eosinophilic airway inflammation and seem to be important drivers of asthma but not COPD pathobiology." (PMID 33203095, 2020). "Although the collected data supports an association between IL-25 and asthma, clinical trials using anti-IL-25 antibodies, as for TSLP and IL-33, have not yet been conducted." (PMID 33255348, 2020). "In addition to its fundamental role in asthma development, TSLP is known to be involved in the pathogenesis of other allergic conditions." (PMID 33050934, 2020). "Given the upstream location of TSLP in the inflammatory cascade and its role in the initiation of the inflammatory response, its blockade is anticipated to have a broad impact on the spectrum of inflammatory responses seen in patients with severe asthma." (PMID 33050934, 2020). "TSLP has also been identified as an important disease gene of asthma in GWAS." (PMID 32397396, 2020). "Like other Th2-associated mediators with protective effects in bleomycin-induced inflammation, it remains unclear how TSLP can have a dual role in Th2-mediated disorders, such as asthma and allergy, and bleomycin-induced inflammation." (PMID 32103153, 2020). "Moreover, a very strong correlation between local periostin and TSLP level suggests positive crosstalk between these two cytokines in asthma." (PMID 33203095, 2020). "Therefore, suppressing TSLP seems like a reasonable strategy for preventing the progression of viral infection-related inflammation and currently tezepelumab, a human monoclonal antibody specific for TSLP, is studied for uncontrolled asthma." (PMID 32120846, 2020). "In asthma, epithelial cells were damaged and functioned abnormally by promoting pathologically tissue repair and inducing chronic airway inflammation through the release of cytokines like TSLP, IL-25 and IL-33." (PMID 32117985, 2020). "The role of TSLP in asthma and allergic inflammation has been extensively investigated." (PMID 33255348, 2020). "Further, we demonstrate that IL-1α alone was elevated in asthmatic compared to non-asthmatic PAEC-ALI cultures during differentiation, compared to other IL-1 family members and key epithelial mediators shown previously to play a role in asthma (IL-8, GM-CSF, TSLP, and TGF-β1)." (PMID 32457454, 2020). "Furthermore, epithelial cell dysfunction acts as a major driver of asthma development, mainly because improper activation and production of IL-25 and TSLP from epithelial cells trigger allergy response." (PMID 33262394, 2020).
asthma (continued). "To date, levels of only periostin or only TSLP have been studied in asthma and COPD patients." (PMID 33203095, 2020). "Furthermore, AD can progress into asthma, a process mediated by thymic stromal lymphopoietin (TSLP) as demonstrated in mouse models of experimental asthma." (PMID 33333859, 2020). "In addition, the expression of TSLP and IL-33 is enhanced in the peripheral blood and lung tissue of patients with severe asthma." (PMID 32397396, 2020). "Although Tezepermab, a biologic that targets TSLP for treatment, was reported to reduce the frequency of asthma exacerbations, the role of ILCS2, including IL25 and IL-33, is not fully understood, and we need to elucidate the full mechanism of its production and develop new treatment options." (PMID 32823491, 2020). "Blocking TSLP with tezepelumab has been shown to be an effective strategy for reducing exacerbations and improving lung function and asthma control in patients with severe, uncontrolled asthma in the phase 2b PATHWAY study." (PMID 33050928, 2020). "Additionally, we noted that 7/12 (58%) patients with asthma had a relatively high level of IS periostin together with sputum eosinophilia and a relatively high level of IS TSLP." (PMID 33203095, 2020). "The analysis of coexistence of sputum eosinophilia (>3%), high sputum periostin, and high sputum TSLP concentration (above the median value of the control group), showed that almost 64% patients with asthma had increased sputum eosinophilia with concomitant elevated levels of IS periostin and TSLP." (PMID 33203095, 2020). "TSLP plays an important role in inducing Th2 inflammation and airway remodeling in asthma." (PMID 32117985, 2020). "For the epithelial environment stage of asthma (allergic sensitization stage), air exposure to allergens induces the secretion of proinflammatory cytokines (Group 1) in the airway epithelium, such as TSLP, IL-6, IL-8, TNF-α, IL-25, IL-33, and GM-CSF." (PMID 31284537, 2019). "Moreover, YPFS significantly reduced pulmonary TSLP production which significantly increased during the remission phase of the asthma recurrence model." (PMID 32076408, 2019). "Furthermore, anti-TSLP treatment has been shown to reduce the frequency of asthma exacerbations and improved FEV1 (% of predicted) in a randomized, double-blind, placebo-controlled trial of uncontrolled asthmatics with moderate to severe asthma." (PMID 31191511, 2019). "Recent studies clearly show that not only Th2 cytokines but also other T-cell-related cytokines such as IL-17A and IL-22 as well as epithelial cell cytokines such as IL-25, IL-33, and thymic stromal lymphopoietin (TSLP) are involved in the pathogenesis of asthma." (PMID 30965592, 2019). "The TSLP could also be an important therapeutic target for reducing asthma and AR in children with AD." (PMID 31223255, 2019). "One recent report showed that TSLP might be an important contributor to corticosteroid resistance of asthma." (PMID 30890137, 2019). "An antibody against TSLP was an effective treatment for asthma." (PMID 30906771, 2019). "The TSLP and the pro-inflammatory cytokines migrate to various pathways entering into systemic circulation and consequently in the airway and nasal mucosa resulting in asthma and AR." (PMID 31223255, 2019). "TSLP assists natural helper cells in inducing corticosteroid resistance in patients with asthma." (PMID 31284537, 2019). "Data showed that YPFS could significantly upregulate the expression of DSG1 and inhibit the overexpression of TSLP in remission phase of the asthma recurrence model." (PMID 32076408, 2019). "Moreover, overexpression of TSLP in epithelial cells in the mouse lung produced a spontaneous asthma-like phenotype." (PMID 31191511, 2019). "For the TSLP variant, the estimated effect size in EGPA was much greater than in asthma, suggesting its association with asthma might be driven by a subset of patients." (PMID 31719529, 2019).
asthma (continued). "Importantly, the long isoform of TSLP has been widely correlated with exacerbated immune responses and the establishment of allergic and asthma in patients with atopic dermatitis." (PMID 31214165, 2019). "Moreover, TSLP, as a key pro-allergic cytokine as reported in EoE and AD, remained higher expression in remission phase of asthma recurrence compared with control." (PMID 32076408, 2019). "Thymic stromal lymphopoietin (TSLP) played an important role in the initiation of allergic inflammation and provided protection against asthma by inducing differentiation of airway epithelium cells and increasing the repair response to airway epithelium injury." (PMID 30906771, 2019). "The activation of this cascade resulted in TSLP production and a strong Th2 response, contributing to the pathophysiology observed in severe bronchiolitis, which eventually in some cases progressed to asthma." (PMID 31214165, 2019). "Notwithstanding its importance at barrier sites, TSLP is well-established as an inducer of Th2 cytokine driven allergic inflammation such as atopic dermatitis, eosinophilic esophagitis, asthma and allergic rhinitis, all mediated by a variety of cells including eosinophils, basophils, and ILC2s." (PMID 31921158, 2019). "Other variants in the TSLP region, independent of rs1837253, are associated with asthma, eosinophil count, eosinophilic oesophagitis and allergic traits." (PMID 31719529, 2019). "Importantly, anti-TSLP has proven effective in ameliorating asthma symptoms in patients, a result that is consistent with the essential role of TSLP in maintaining memory Th2 populations in vivo." (PMID 31164097, 2019). "Collectively, the dysfunction of DSG1 during the remission phase might contribute to bronchial barrier compromise and overexpression of TSLP, which facilitated asthma relapse in a faster and more severe pattern." (PMID 32076408, 2019). "Additionally, TSLP assists natural helper cells to induce corticosteroid resistance in patients with asthma." (PMID 29670037, 2018). "TSLP expression is increased in the airway epithelium and lamina propria of patients with severe asthma even during high-dose inhaled or oral corticosteroid therapy, suggesting the potential of anti-TSLP treatment in corticosteroid resistant severe asthma with increased Th2 inflammation." (PMID 29320511, 2018). "Interestingly, anti-TSLP alleviates airway inflammation in a dust mite-induced mouse model of asthma." (PMID 30057581, 2018). "Thymic stromal lymphopoietin (TSLP), an interleukin 7 (IL-7)-like cytokine associated with several allergic diseases including asthma, has been suggested to be a liaison between RTIs and asthma development." (PMID 29343779, 2018). "These two studies indicate that TSLP is an attractive therapeutic target in asthma." (PMID 30057581, 2018). "Skin allergen exposure in the presence of TSLP may trigger progression from atopic dermatitis to asthma." (PMID 30304837, 2018). "Margolis and colleagues found in the studies that this genetic variant of TSLP rs1898671 was associated with a reduced likelihood of a persistent form of AD and it did not cause any additional risk of asthma." (PMID 30304837, 2018). "TSLP and TARC/CCL17 expression is associated with airway obstruction in patients with asthma." (PMID 29670037, 2018). "Importantly, administration of sf TSLP decreased airway hyperreactivity and inflammation in a mouse model of asthma." (PMID 30057581, 2018). "However, our present study demonstrated similar increased plasma TSLP levels in patients with asthma, COPD, and patients with features of ACO with those in control subjects." (PMID 29580282, 2018). "The viral and genetic risk factors for the TSLP and TSLPR heterocomplex may have important roles in the onset of asthma." (PMID 29670037, 2018). "The TSLP–TSLPR heterocomplex axis may play a fundamental role in the innate–adaptive interface in the pathology of asthma." (PMID 29670037, 2018).